EGFR (epidermal growth factor receptor)
Diseases named in the same sentence as EGFR in open-access papers (continued):
Sharing a sentence is not in itself a finding about the gene and the disease.
tumor (continued). "Nevertheless, EGFR expression in the tumour was significantly associated with longer TTP in the multivariate analysis (adjusted HR 0.23, 95% CI 0.086–0.63; P=0.004)." (PMID 19127259, 2009). "Of the 36 remaining cases, Chr7 loss was observed in 1 (3%) primary tumour, Chr7 disomy in 10 (28%) cases, Chr7 polysomy in 17 (47%) and EGFR gene amplification in 8 (22%) cases." (PMID 19293803, 2009). "Previous studies indicated cytoplasmic EGFR immunostaining was associated with high tumor stage, grade and poor prognosis in RCCs." (PMID 19747398, 2009). "EGFR is widely expressed in different tumor types and strong expression is associated with higher risk of recurrence/metastasis, poorer survival, and resistance to chemotherapy/radiotherapy." (PMID 19750187, 2009). "Tumor signaling pathway components that work synergistically with EGFR or compensate for the loss of EGFR-initiated signaling are likely to be ideal targets for multi-targeted therapy." (PMID 19284526, 2009). "Increased EGFR signalling has been associated with progression to invasion and metastasis in tumours." (PMID 19888222, 2009). "This inconsistency of response is likely because of the fact that few MM tumours possess the activating EGFR mutations that correlate with tyrosine kinase inhibitor efficacy." (PMID 19755995, 2009). "Kras mutations predict profound tumor resistance to drugs that target the epidermal growth factor receptor and have also been associated with tumor stage and risk of recurrence." (PMID 19240792, 2009). "The combination regimen was associated with clinically meaningful tumour response and stabilisation and the PD markers in skin reflected inhibition of the EGFR signalling at all DLs." (PMID 19238629, 2008). "Tumour molecular markers, particularly EGFR protein expression, EGFR gene copy number and the presence of mutations in the EGFR tyrosine-kinase domain, have also been studied to determine which patients are most likely to benefit from erlotinib therapy." (PMID 18983643, 2008). "Direct sequencing using DNA from tumour specimens was performed by a central laboratory to detect EGFR mutations." (PMID 18283321, 2008). "Tumor cells whose growth depends on constitutive kinase activity of EGFR caused by mutation are sensitive to EGFR inhibitors, such as gefitinib and erlotinib, whereas those with the wild-type gene do not respond to the drugs." (PMID 19517027, 2008). "Over-expression and increased activity of EGFR are key characteristics of human tumors and are frequently linked to more aggressive tumor behaviors, including increased proliferation, metastasis, and therapeutic resistance." (PMID 18302761, 2008). "Epidermal growth factor receptor mutations were detected in the primary tumours of five (20%) patients; of these, three of them were the well-characterised ‘hotspot’ mutations in exon 19 (Del746-750 and E746V; case nos." (PMID 19238633, 2008). "None of the studied proteins was associated with menopausal status, tumor size, lymph node status, tumour stage and PR hormonal status, which is in accordance with the majority of reports on EGFR expression." (PMID 18522728, 2008). "In this study, the mutation status of EGFR and K-RAS as well as the EGFR and p-EGFR expressions on the primary tumours and the corresponding metastatic lesions were evaluated in 25 patients with advanced NSCLC." (PMID 19238633, 2008). "Generally, about half of the patients with BRCA1 gene mutations present the phenotype ER(-)/HER2(-)/EGFR(+) of the basal type of tumor, which is usually associated with poor prognosis." (PMID 18405391, 2008). "Although elevated EGFR expression in tumours is usually associated with more aggressive disease and poor clinical prognosis; in some studies EGFR expression was found to have no prognostic significance." (PMID 18268492, 2008). "It has been reported that epidermal growth factor receptor (EGFR) expression is associated with tumour proliferation, angiogenesis and invasiveness in many tumours." (PMID 19014499, 2008).
tumor (continued). "Seventy tumours (23% in the whole tumour set, 9% in Caucasian, 34% in Asian specimens) had EGFR kinase domain mutations with only one of them occurring concurrently with an LKB1 mutation (P=0.002)." (PMID 18594528, 2008). "For these tumours, we found a statistically significant association between the evaluations obtained by the two methods, for the EGFR (Mann–Whitney test, P<0.001) and the HER2 (Kruskal–Wallis test, P<0.001) receptors." (PMID 18985033, 2008). "All patients who experienced progressive disease on gefitinib were wild type regarding the EGFR mutation status in both primary tumours and metastases (nos." (PMID 19238633, 2008). "Among the isolated BAC clones in which the tumor/normal ratio exceeded 1.3 (gain) or was less than 0.75 (loss), a clone on 7p12 containing the gene for epidermal growth factor receptor (EGFR) was amplified." (PMID 18940013, 2008). "Association studies between EGFR alterations and the clinical pathological features of the tumours were performed." (PMID 18199332, 2008). "Among the five patients with EGFR mutations in primary tumours, one patient concomitantly had K-RAS mutation (G12C with deletion in exon 19)." (PMID 19238633, 2008). "Numerous studies have shown the association of EGFR with tumor proliferation, invasiveness and angiogenesis." (PMID 18928570, 2008). "Epithelial growth factor receptor (EGFR) and KRAS mutation status have been reported as predictive markers of tumour response to EGFR inhibitors." (PMID 18495026, 2008). "Other groups have developed bsAb-based molecules that simultaneously target two tumour-associated antigens such as EGFR and insulin growth factor receptor (IGFR) or carcinoembryonic antigen (CEA) and ErbB2." (PMID 18841159, 2008). "The frequency of EGFR–FISH positive cases was higher in EGFR mutation positive (P=0.008) or EGFR-IHC positive tumours (P<0.00001)." (PMID 18283317, 2008). "All the five patients with stable disease on gefitinib carried EGFR mutations in their primary tumours (nos." (PMID 19238633, 2008). "The correlation of the clinical parameters for the cases for which both mutation and FISH analysis was possible, showed a significant association between EGFR alterations and tumour size." (PMID 18199332, 2008). "In models of human breast cancer, inhibition of YB-1 with a dominant negative mutant (interferes with the DNA binding activity of the protein [S102A]) slows tumor cell growth, and this is associated with the downregulation of EGFR and HER-2." (PMID 18925950, 2008). "Consistent with the results of previous studies, this study revealed that increased Id-1 expression was correlated with high grade and advanced stage tumours and that Id-1 expression was also significantly associated with EGFR expression." (PMID 19014499, 2008). "The tumour with a concurrent EGFR and LKB1 mutation had a missense mutation of LKB1 outside the kinase domain (R426W)." (PMID 18594528, 2008). "In EHCC, EGFR expression is associated with clinical factors involved in tumour progression and invasion." (PMID 18087285, 2008). "In 75 out of 84 (89.3%) specimens, a sufficient number of cancer cells remained for FISH analysis after tumour cell dissection for EGFR gene mutation analysis." (PMID 18087280, 2008). "The two major findings in the present study provide additional support for the use of serum DNA as an alternative to tumour samples for detection of EGFR mutations in patients with advanced NSCLC." (PMID 17848912, 2007). "First, these results demonstrate that EGFR mutation status in serum DNA was the same as in tumour samples in almost every patient." (PMID 17848912, 2007). "Hyperactivation of MAPK was investigated using a recently described MAPK signature, and was linked to tumour phenotype, ER and EGFR and/or ErbB2 overexpression." (PMID 17700572, 2007). "The tumor cells in these patients have somatic mutations in the EGFR kinase domain that constitutively activate EGFR." (PMID 18030354, 2007).
tumor (continued). "Sequencing of the epidermal growth factor receptor (EGFR) gene in a large number of tumor samples has identified somatic activating mutations in the tyrosine-kinase pocket of EGFR." (PMID 17973572, 2007). "Here, we examined a total of 261 tumor samples, predominantly adenocarcinomas, specifically for genetic alterations in genes encoding major signaling proteins in the EGFR signaling pathway." (PMID 17487277, 2007). "In a multivariate survival analysis adjusting for T stage, N stage, tumour grade, vascular invasion and age, EGFR overexpression was independently associated with worse survival time (P<0.001) (HR (95% CI)=1.93 (1.44–2.57))." (PMID 17311026, 2007). "EGFR mutations were detected in the tumour samples of eight patients and in the serum samples of seven patients." (PMID 17848912, 2007). "Complete or partial tumour response was more frequently associated with positive EGFR expression (>15% tumour cell staining) (P-value=0.008; OR (95% CI)=3.59 (1.37–9.43))." (PMID 17311026, 2007). "The researchers first measured the ability of gefitinib to cause apoptosis (genetically programmed cell death) in NSCLC cell lines (tumor cells adapted to grow indefinitely in dishes) that had the EGFR deletion, the L858R mutation, or normal EGFR." (PMID 17973572, 2007). "EGFR mutation detection was performed by sequencing exons 18, 19 and 21 in tumours of all patients (n=86) and matched-normal tissue (n=22) or blood (n=3) of patients carrying EGFR mutations." (PMID 18000506, 2007). "On the other hand, tumour growth control was significantly higher (P=0.013) in patients who presented the classical EGFR mutations compared to that of patients with wild-type EGFR, as already has been reported." (PMID 18000506, 2007). "Positive EGFR expression (>18% tumour cell staining) was significantly associated with complete pathological response to preoperative HDREB (P-value <0.001; OR (95% CI)=7.12 (2.3–21.7))." (PMID 17311026, 2007). "The basal-like group was subsequently defined, using immunohistochemistry, as being ER- PR- ERBB2-, with tumor cells expressing at least one basal-myoepithelial marker such as KRT 5/6 or KRT 14 in association with EGFR or KIT." (PMID 17417968, 2007). "Somatic mutations in the EGFR tyrosine-kinase domain have been correlated with reduced tumour size as a result of treatment with gefitinib." (PMID 17626639, 2007). "Inhibitors of the EGFR tyrosine kinase have proven useful in the therapy of certain cancers, in particular NSCLCs possessing activating mutations in the EGFR kinase domain, but the mechanisms of tumor cell killing are still unclear." (PMID 17973573, 2007). "We then examined 93 WGA-treated DNA tumor samples for mutations in EGFR pathway genes and a set of exploratory genes." (PMID 17487277, 2007). "It would be interesting to also study EGFR mutations and EGFR amplification in tumour samples from these patients." (PMID 17876336, 2007). "Because EGFR is expressed and associated with poor prognosis and a more malignant phenotype in many neoplasms, it has been investigated as a potential target for cancer therapy." (PMID 17876336, 2007). "ROC curve-derived cutoffs were used to analyse the association of EGFR overexpression, tumour response and several clinicopathological features including survival." (PMID 17311026, 2007). "The tumor cells are dependent on, or addicted to, the EGFR mutated oncogene for both maintenance of the malignant phenotype and cell survival." (PMID 17973572, 2007). "EGFR mutations were strong correlations between both EGFR mutation status in the tumour samples and serum samples and objective response to gefitinib (P<0.001)." (PMID 17848912, 2007). "Recent studies have found EGFR protein expression in tumor tissues to be strongly associated with hormone refractory status." (PMID 17598908, 2007). "The detection of EGFR mutations in serum provides a unique and potentially valuable tumour marker for prediction of response and prognosis." (PMID 17848912, 2007).
tumor (continued). "The serum assay to detect EGFR mutations circumvents the need for tumour tissue and merits further validation of the use of serum DNA to detect EGFR mutations as a predictor of response to, and survival on gefitinib in prospective studies." (PMID 17848912, 2007). "In vivo, the EGFR-signatures were of prognostic value, were associated with tumor subtype, and were uniquely associated with the high expression of distinct EGFR-RAS-MEK pathway genes." (PMID 17663798, 2007). "In six of the patients, the same EGFR mutation was detected in both the tumour sample and the serum sample." (PMID 17848912, 2007). "Numerous studies suggest that gefitinib has fairly effective anti-tumor activity, especially for tumors with EGFR gene mutations." (PMID 18021415, 2007). "Over the last three years, we have carried out mutational analysis of EGFR in tumor samples from nearly 300 NSCLC patients [and unpublished data]." (PMID 17877814, 2007). "This suggestion is supported by the findings of a prospective trial of gefitinib in which 4 of 16 patients selected for tumours with EGFR mutations didn't respond to gefitinib." (PMID 17626639, 2007). "Likely via its ability to upregulate gene expression, nuclear EGFR pathway is associated with major characteristics of more aggressive tumours: increased proliferative potential, nitric oxide synthesis, and accelerated G1/S cell cycle progression." (PMID 16434982, 2006). "As it is often difficult to obtain a sufficient tumour sample from patients with inoperable NSCLC to detect EGFR mutations by direct sequencing, a method of detecting EGFR mutations in other specimens needed to be established." (PMID 17060940, 2006). "Some investigators subsequently found that EGFR mutations are one of the strong determinants of tumour response to EGFR tyrosine kinase inhibitors." (PMID 17060940, 2006). "These agents have demonstrated clinical activity in 8–20% of patients with non-small-cell lung cancer (NSCLC), especially in a subset of NSCLC patients whose tumours contain mutations involving the ATP binding pocket of the EGFR." (PMID 16622439, 2006). "Subsequently, it was demonstrated that the tumours with EGFR mutations are highly sensitive to gefitinib and the patients with EGFR mutations survived for a longer period after gefitinib treatment." (PMID 16552419, 2006). "Overall, 10 of 11 patients with EGFR mutations in exon 19 or 21 showed tumour regression with gefitinib treatment, compared to only two of 14 patients with wild-type EGFR." (PMID 17047654, 2006). "Increased immunoreactivity of nuclear FABP7 correlated with poor prognosis of GBM, particularly in younger patients, and we sought to identify the molecular mechanism underlying this association by investigating EGFR expression in this tumor type." (PMID 16623952, 2006). "Epidermal growth factor receptor mutations were observed in 60 tumours (39.0%), all of which were adenocarcinoma." (PMID 16052218, 2005). "It is also known that EGFR mutations activated the antiapoptotic protein Akt, and that patients whose tumours have activated Akt are more sensitive to TKIs than patient whose tumours are phospho-AKT negative." (PMID 16288303, 2005). "PC-9 tumour cells harbour an activating mutation of the EGFR gene and are highly sensitive to ZD6474 treatment in vitro." (PMID 15928657, 2005). "The type III epidermal growth factor mutation variously named, EGFRvIII, ΔEGFR, de2-7EGFR and mEGFR is the most common mutation in the EGFR gene and is frequently found in tumours of the breast, ovary, prostate, lung and in particular those of the brain." (PMID 16189524, 2005). "Activation of EGFR has been shown to result in accelerated tumour growth and is associated with a poor patient prognosis in many solid tumours." (PMID 15611794, 2005). "The recent discovery of somatic activating mutations in the tyrosine kinase domain of the EGFR gene in the tumour brings new hope of improved ability to predict response to gefitinib." (PMID 15942627, 2005).